RHBDD3 (rhomboid domain containing 3)
Synonyms: C22orf3; PTAG; HS984G1A
Tractability: Antibody: UniProt predicts a signal peptide or a membrane-spanning region. PROTAC: ubiquitination databases record sites on it.
Gene: Protein-coding gene on chromosome 22 (29,259,852 to 29,268,221, reverse strand). Ensembl gene ENSG00000100263.
Subcellular location: Membrane
Subcellular location (Human Protein Atlas): Microtubules
Gene Ontology:
Molecular function: serine-type endopeptidase activity
Cellular component: membrane
Genetic constraint (gnomAD): Loss-of-function variants: 38 observed, 26.37 expected, observed/expected ratio (o/e) 1.44, 90% interval 1.11 to 1.84. The synonymous counts are far from expectation, so gnomAD's model fits this gene poorly and the ratio says little. Missense variants: 482 observed, 417.43 expected, observed/expected ratio (o/e) 1.15, 90% interval 1.07 to 1.25. Synonymous variants: 249 observed, 196.46 expected, observed/expected ratio (o/e) 1.27, 90% interval 1.14 to 1.41.
Homologues: Orthologues: chimpanzee RHBDD3 (99% identical), macaque RHBDD3 (93% identical), pig RHBDD3 (84% identical), dog RHBDD3 (83% identical), rabbit RHBDD3 (78% identical), guinea pig RHBDD3 (77% identical), rat Rhbdd3 (77% identical), mouse Rhbdd3 (76% identical), tropical clawed frog rhbdd3 (33% identical), zebrafish rhbdd3 (30% identical). Paralogues in human: RHBDD2 (16% identical), RHBDD1 (14% identical).
Diseases named in the same sentence as RHBDD3 in open-access papers:
RHBDD3 is named in the same sentence as 11 diseases in open-access papers, as found by Europe PMC text mining. Sharing a sentence is not in itself a finding about the gene and the disease. The quoted sentences say what the papers report.
autoimmune disease (2 papers, 2017 to 2023). A disorder resulting from loss of function or tissue destruction of an organ or multiple organs, arising from humoral or cellular immune responses of the individual to their own tissue constituents. "RHBDD3 negatively controls the activation of DCs and maintains the balance of regulatory T cells and TH17 cells by inhibiting the production of IL-6 by DCs, thus contributing to the prevention of autoimmune diseases." (PMID 29236770, 2017).
colitis (1 paper, 2024). Inflammation of the colon. "Moreover, Rhbdd3 has been reported as a suppressor of the production of IL-6 by inhibiting K63-linked polyubiquitination of NEMO in dendritic cells to control Th17 cell-mediated colitis caused by excessive activation of dendritic cells." (PMID 38346956, 2024).
Crohn disease (1 paper, 2017). A gastrointestinal disorder characterized by chronic inflammation involving all layers of the intestinal wall, noncaseating granulomas affecting the intestinal wall and regional lymph nodes, and transmural fibrosis. "For RHBDD3, its downregulation in patients with rheumatoid arthritis, ulcerative colitis and Crohn’s disease may be beneficial in preventing auto-immune aggression." (PMID 29236770, 2017).
uveal melanoma (1 paper, 2025). A melanoma derived from melanocytes of the uveal tract. "In the uveal melanoma cohort, a six‐molecule signature (ARPC1B, BTBD6, GUSB, KRTCAP2, RHBDD3, and SLC39A4), which was associated with glycolysis and the immune response, was established and used for survival prediction and risk stratification of these patients." (PMID 39830021, 2025).
RHBDD3 also shares sentences with these, for which no sentence is quoted: Autoimmunity (1 paper); infectious disease (1); pituitary tumor (1); rheumatoid arthritis (1); tuberculosis (1); ulcerative colitis (1); viral infection (1).